HDGF (heparin binding growth factor)
Diseases named in the same sentence as HDGF in open-access papers (continued):
Sharing a sentence is not in itself a finding about the gene and the disease.
urothelial carcinoma of the bladder (9 papers, 2021 to 2023). "It has been reported that NSUN2-YBX1-mediated m5C modification maintained the stability of HDGF mRNA in human urothelial carcinoma of the bladder." (PMID 37161388, 2023). "NSUN2 and YBX1 drive the pathogenesis of urothelial carcinoma of the bladder by targeting the m5C methylation site in the 3′-untranslated region of HDGF." (PMID 37398932, 2023). "NSUN2 and YBX1 have been shown to drive the pathogenesis of human bladder urothelial carcinoma (UCB) by targeting m5C methylation sites in the hepatoma-derived growth factor (HDGF) 3′ UTR." (PMID 34188972, 2021). "For example, NSUN2 and YBX1 drive the onset of human urothelial carcinoma of the bladder (UCB) by targeting the m5C methylation site in the 3′ untranslated region of hepatoma-derived growth factor (HDGF)." (PMID 33928086, 2021). "Moreover, upregulated NUSN2, YBX1, and HDGF expression levels predicted a poorer survival rate in patients with urothelial carcinoma of the bladder." (PMID 35365216, 2022). "In human urothelial carcinoma of bladder, NSUN2 targets and regulates HDGF through m5C methylation, thereby promoting tumorigenesis." (PMID 33400376, 2021). "It was reported that NSUN2 could cooperate with Y-box-binding protein 1 (YBX1), an m5C ‘reader’, to drive pathogenesis of human urothelial carcinoma of the bladder (UCB) by stabilizing oncogenic mRNAs, such as heparin-binding growth factor (HDGF), via m5C methylation." (PMID 37612540, 2023). "NSUN2 and its reading protein Y-box binding protein 1 (YBX-1) are highly expressed in human urothelial carcinoma of the bladder (UCB) and act as oncogenes in an m5C-dependent manner, promoting the development of UCB by increasing the mRNA stability of heparin-binding growth factor (HDGF)." (PMID 35574373, 2022).
ovarian carcinoma (8 papers, 2012 to 2025). A malignant neoplasm originating from the surface ovarian epithelium. "Loss of the endosulfatase HSulf-1 is common in ovarian cancer, upregulates heparin binding growth factor signaling and potentiates tumorigenesis and angiogenesis." (PMID 25225614, 2014). "HDGF has recently been implicated in the pathogenesis of several other cancers but its role in ovarian cancer remains unknown so far." (PMID 22442705, 2012). "In a range of tumor types, including NSCLC, ovarian cancer, oral cancer, gastric cancer and melanoma, HDGF is overexpressed, and its higher expression is strongly correlated with poor prognosis." (PMID 37301856, 2023). "Further, they confirmed the role of HDGF as a new target for cancer treatment through silencing of HDGF, which inhibited the proliferation of ovarian cancer cells." (PMID 35887030, 2022). "We confirmed expression of HDGF in various ovarian cancer cells and validated binding selectivity to +AuNPs by Western blot analysis." (PMID 22442705, 2012). "To demonstrate functional effects we knocked down HDGF in A2780 cells, by using siRNA (KD-siRNA) and looked at the proliferation of the ovarian cancer cells." (PMID 22442705, 2012). "One of the proteins we chose to examine more closely is HDGF, which was identified as a possible ovarian-cancer-specific mitogen because it was found only with the lysates of the malignant cells, and only on the +AuNPs." (PMID 22442705, 2012). "Upon knockdown of HDGF expression, we observed that the proliferation of ovarian cancer cells was vastly reduced." (PMID 22442705, 2012). "The potential of our method for identifying therapeutic targets was demonstrated through silencing of HDGF by siRNA, which inhibited proliferation of ovarian cancer cells." (PMID 22442705, 2012). "As seen in the Western blot, HDGF is expressed across various ovarian cancer cell lines, with the highest expression in A2780 cell line and the lowest in normal OSE." (PMID 22442705, 2012). "In this study, we established HDGF as a possible therapeutic target for ovarian cancer by use of proteomic analysis and expression levels in cancer cells." (PMID 22442705, 2012). "Silencing of HDGF by siRNA resulted s inhibition in proliferation of ovarian cancer cells." (PMID 22442705, 2012). "We first determined the expression levels of HDGF in various ovarian cancer cell lines." (PMID 22442705, 2012). "In addition, silencing of HDGF results in significant inhibition of proliferation of ovarian cancer cells (∼70%) as compared to the scrambled siRNA (sc-siRNA) control." (PMID 22442705, 2012). "We then investigated the functional consequences of the presence of HDGF in ovarian cancer." (PMID 22442705, 2012). "Interestingly, proteins such as CCNE1, FASN, HDGF, MCM7, PIGR, PTK2, or TRA2B have been described as having a prognostic relation with some other type of gynecological cancer (breast, cervical or ovarian cancer)." (PMID 34680205, 2021). "To date, it has not been established if HDGF has a role in ovarian cancer." (PMID 22442705, 2012).
colon carcinoma (6 papers, 2013 to 2024). "Lepourcelet and coworkers reported the correlation of HDGF reexpression with mismatch repair proficient colon carcinoma in contrast to carcinomas deficient for this type of DNA repair suggesting an involvement of HDGF in this kind of biological process." (PMID 23305559, 2013). "In colon cancer cells, mir-195-5p binds to the hepatoma-derived growth factor (HDGF) and suppresses its expression, promoting cisplatin-induced apoptosis." (PMID 38328550, 2024). "Vascular endothelial growth factor (VEGF) is endothelial cell specific heparin-binding growth factor, which is critical for the proliferation and metastatic potential of colon carcinoma cells." (PMID 26236156, 2015). "Both Prune and HDGF are overexpressed in breast and colon cancers." (PMID 26643252, 2015).
prostate carcinoma (6 papers, 2018 to 2024). A carcinoma that arises from epithelial cells of the prostate gland. "In conclusion, the downregulation of HDGF significantly is associated with the inhibition of the migration and invasion in prostate cancer cells, at least in part, by suppressing EMT process and the expression of MMP9 and MMP2, which play an important role in the tumorigenesis of PCa." (PMID 29300772, 2018). "miR-939 deactivates the Wnt path by controlling hepatoma-derived growth factor (HDGF) and modulates prostate cancer." (PMID 35201496, 2021). "It is shown that HDGF knockdown reduces prostate cancer cellular migration and invasion in both androgen-sensitive LNCaP cells and androgen-insensitive DU145 and PC3 cells." (PMID 29300772, 2018). "It has previously been shown that HDGF is overregulated in prostate cancer cells compared to normal prostate cells, which is correlated with cellular migration and invasion of prostate cancer." (PMID 29300772, 2018). "In conclusion, our data suggested that HDGF knockdown inhibits cellular migration and invasion in vitro of prostate cancer via modulating epithelial-mesenchymal transition (EMT) signaling pathway, as well as MMP2 and MMP9 signaling pathway." (PMID 29300772, 2018). "Here, the molecular mechanisms of HDGF in prostate cancer is investigated." (PMID 29300772, 2018). "Furthermore, Western blot analysis reveals that HDGF knockdown inhibits epithelial-mesenchymal transition (EMT) of prostate cancer cells by upregulation of protein E-cadherin and downregulation of proteins N-cadherin, Vimentin, Snail and Slug." (PMID 29300772, 2018). "While the prognostic value of HDGF has not yet been evaluated before, previous studies have shown that downregulation of HDGF inhibited migration and invasion of prostate cancer cells, and HDGF activated the MAPK/ERK pathway via KRAS and RhoA mediation in cell line models of prostate cancer." (PMID 39402324, 2024). "With the 5-gene prostate cancer metastasis signature panel comprised of U2AF2, RUVBL1, STMN1, HDGF, and FABP4, we further assessed the power of prediction of this gene signature panel in two different, independent public patient datasets (Grasso CS, Nature, 2012; Varambally S CS, Cancer Cell, 2005)." (PMID 39402324, 2024).
cervical carcinoma (5 papers, 2014 to 2025). A carcinoma arising from either the exocervical squamous epithelium or the endocervical glandular epithelium. "For example, lncRNA DLG1-AS1 enhances the resistance of cervical cancer cells to gemcitabine by regulating the miR-16-5p/HDGF pathway." (PMID 40764609, 2025). "By adenovirus gene delivery, HDGF overexpression enhanced, whereas HDGF knockdown perturbed the tumorigenic behaviors of cervical cancer cells." (PMID 25421244, 2014). "The HDGF mRNA and protein level were significantly higher in malignant cervical cancer cells compared with primary ones." (PMID 25421244, 2014). "The growth of cervical cancer cells (Hela cells) was enhanced by HDGF treatment." (PMID 25421244, 2014).
lymph node metastasis (5 papers, 2013 to 2024). "Multivariate Cox regression analysis demonstrated that high HDGF expression and lymph node metastasis were independent prognostic indicators for reduced OS in CRC patients." (PMID 26296979, 2015). "HDGF expression was significantly related to histological differentiation (p = 0.035) and lymph node metastasis (p = 0.000)." (PMID 26296979, 2015). "Univariate and multivariate Cox regression analysis showed that high HDGF expression and lymph node metastasis were the strong independent prognostic indicators for reduced OS in CRC patients." (PMID 26296979, 2015). "Our data showed that HDGF expression was significantly related to histological differentiation and lymph node metastasis in CRC." (PMID 26296979, 2015). "In addition, other clinical parameters including histological differentiation, clinical stage, lymph node metastasis, and HDGF/β-catenin expression were also significant prognostic indicators for OS in CRC patients." (PMID 26296979, 2015). "Interestingly, we observed that nuclear expression of HDGF protein was significantly associated with the survival time for EC patients in depth of myometrial invasion (≧1/2), lymph node metastasis, without lymph node metastasis, and FIGO stage III." (PMID 24692842, 2014). "Moreover, elevated nuclear HDGF levels were correlated with lymph-vascular space invasion (LVSI; p < 0.05), lymph node metastasis (LNM; p < 0.001), recurrence (p < 0.001) and advanced grade (AG; p < 0.001)." (PMID 25421244, 2014).
oral cancer (5 papers, 2019 to 2023). "HDGF expression has been hypothesized to play an important role in tumorigenesis and angiogenesis in oral cancer, which may be associated with the induction of angiogenic factors, leading to a more aggressive pattern of growth and poor prognosis." (PMID 31711427, 2019). "In oral cancer, HDGF has been observed to induce VEGF gene expression by upregulating HIF-1α and NF-κB." (PMID 34782720, 2022). "VEGF overexpression is closely related to advanced disease and poor survival in in vitro experiments and bioinformatics, revealing a novel HDGF/HIF-1α/VEGF axis in oral cancer prognosis." (PMID 34322156, 2021). "In this study, for the first time, we demonstrated that HDGF enhanced VEGF expression in oral cancer cells at the mRNA level, protein level and secretion level with a dose-dependent manner." (PMID 31711427, 2019). "In summary, this study is the first to report the association between HDGF and VEGF and prognosis in oral cancer." (PMID 31711427, 2019). "Therefore, the HDGF/nucleolin/HIF-1α/VEGF axis is a very attractive target for oral cancer treatment." (PMID 31711427, 2019). "According to TCGA data analysis (n = 522, oral cancer; n = 566, head and neck cancer [TCGA, Provisional cohort]), the HDGF and VEGF mRNA expression profile exhibited a strong positive correlation (P = 0.0107; R2 = 0.01247, oral cancer; P = 0.0001; R2 = 0.02643, head and neck cancer)." (PMID 31711427, 2019). "In addition, HDGF has been shown to promote tumor angiogenesis in oral cancer and HCC." (PMID 34782720, 2022). "TCGA and immunohistochemical analysis revealed a positive correlation between HDGF and VEGF expression in oral cancer tissues." (PMID 31711427, 2019). "Together, these results implied that HDGF stimulated AKT/HIF-1α/NF-κB signaling, thereby modulating VEGF expression in oral cancer cells." (PMID 31711427, 2019). "The current study was designed to elucidate the regulatory mechanism between HDGF and vascular endothelial growth factor (VEGF) and the clinical impact of oral cancer." (PMID 31711427, 2019). "Recombinant HDGF significantly increased VEGF gene and protein expression in oral cancer SCC4 cells in a dose-dependent manner." (PMID 31711427, 2019). "Through correlation analysis of the immunohistochemistry assay and TCGA data, these results provided support for the interaction between HDGF and VEGF expression in oral cancer." (PMID 31711427, 2019). "Furthermore, HDGF binds to membrane NCL to activate the HIF-1α/VEGF axis, and Akt/NFκB signaling contributes to poor disease control in oral cancer." (PMID 37827291, 2023). "Human oral cancer SCC4 and SAS cells were treated with recombinant HDGF protein." (PMID 31711427, 2019). "Our data have shown that exogenous HDGF protein not only stimulated the phosphorylation levels of AKT and IκB but also increased the protein levels of the transcriptional factors HIF-1α and NF-κB p65 in oral cancer cells." (PMID 31711427, 2019). "We have previously demonstrated that HDGF overexpression contributes to oncogenic processes and constitutes a novel negative prognostic factor for oral cancer." (PMID 31711427, 2019). "Thus, the current study was designed to elucidate the possible interaction or regulatory mechanism between HDGF and VEGF and the possible clinical impact in oral cancer." (PMID 31711427, 2019). "Because HDGF overexpression is correlated with angiogenesis and tumorigenesis, including in oral cancer, we investigated whether there was a relationship between HDGF and VEGF expression in oral cancer and head and neck cancer." (PMID 31711427, 2019). "Hepatoma-derived growth factor (HDGF) participates in angiogenesis and represents a negative prognostic factor in oral cancer." (PMID 31711427, 2019).
esophageal cancer (4 papers, 2010 to 2025). A primary or metastatic malignant neoplasm involving the esophagus. "In a previous study, a possible association between the expression of HDGF and the radiosensitivity of esophageal cancer cells was reported." (PMID 32545762, 2020). "HDGF is positively associated with radioresistance in esophageal cancer." (PMID 34376200, 2021). "Further studies are still necessary to determine the precise role of HDGF in relation to the poor prognosis in esophageal cancer." (PMID 32545762, 2020). "HDGF was strongly expressed in radiation-sensitive esophageal cancer cells, and radiation therapy showed higher treatment efficacy in patients with a high expression of HDGF, in comparison to those with low HDGF expression levels." (PMID 32545762, 2020). "One possible explanation was that esophageal cancer cells with high HDGF expression levels have high proliferative activity, and thus finally cause an unfavorable outcome, regardless of the transiently observed high treatment efficacy." (PMID 32545762, 2020).
Ewing sarcoma (4 papers, 2009 to 2022). A small round cell tumor that lacks morphologic, immunohistochemical, and electron microscopic evidence of neuroectodermal differentiation. "Our RT-PCR analysis confirmed that Ewing's sarcoma cells expressed higher levels of HDGF with respect to putative normal controls (CD34 positive cells and normal muscle tissues)." (PMID 19144156, 2009). "• The HDGF-ALCAM axis promotes metastasis of Ewing sarcoma by means of regulating GTPases." (PMID 34100888, 2021). "The oncogenic function of CDC42 in Ewing sarcoma is further supported by a study demonstrating that CDC42 activation and upregulation is partly responsible for the role of hepatoma-derived growth factor (HDGF) in local invasion." (PMID 36594908, 2021).
gastric tumor (4 papers, 2021 to 2023). "IGF2BP3 directly recognizes and binds to the m6A modification site of METTL3-mediated HDGF mRNA and enhances the stability of HDGF, thereby promoting gastric tumor angiogenesis." (PMID 35572524, 2022).
glioblastoma (4 papers, 2019 to 2022). The most malignant astrocytic tumor (WHO grade IV). "Studies have shown that glioblastoma stem cell-like cells can express HDGF to directly induce tumor angiogenesis." (PMID 34895232, 2021). "Glioblastoma cells stimulate angiogenesis and consolidate existing vasculature by secreting regulatory growth factors like vascular endothelial growth factor (VEGF) or hepatoma-derived growth factor (HDGF)." (PMID 35022057, 2022).
gastritis (3 papers, 2021 to 2023). Inflammation of the stomach. "For instance, neutrophils stimulate an inflammatory TNF-α/HDGF/COX-2 signaling cascade that plays an important role during Helicobacter pylori-induced gastritis and gastric carcinogenesis." (PMID 37827291, 2023). "Importantly, HDGF participates in Helicobacter Pylori-induced neutrophils recruitment, gastritis and gastric carcinogenesis." (PMID 34895232, 2021). "Hepatoma-derived growth factor (HDGF), overexpressed in GC patients and after H. pylori infection, seems to participate in H. pylori-induced neutrophils recruitment, gastritis and gastric carcinogenesis." (PMID 33810350, 2021).
liver fibrosis (3 papers, 2015 to 2023). "Recently, HDGF overexpression has also been delineated to contribute to liver fibrosis, epithelial-mesenchymal transition and metastasis." (PMID 25938538, 2015). "Hepatoma-derived growth factor (HDGF) overexpression is involved in liver fibrosis and carcinogenesis." (PMID 25938538, 2015). "In this case, we assume that HSC were not activated by the engulfment of HIV+ hepatocyte ABs which contain hepatocyte-specific proteins (such as HDGF) sensed by HSC, and liver fibrosis is not activated." (PMID 36982417, 2023).
lung adenocarcinoma (3 papers, 2019 to 2022). A carcinoma that arises from the lung and is characterized by the presence of malignant glandular epithelial cells. "In previous study, our team had shown the interaction of β-catenin and HDGF or DDX5 in Lung Adenocarcinoma." (PMID 31032220, 2019). "For lung adenocarcinoma, we found that the expression levels of three genes, GPR15, HDGF, and AHHR, were associated with increased smoking-related mutational signature, while an inverse association was observed for the other four genes, NWD1, KCNQ1, CAPN8 and RPS6KA1." (PMID 32928150, 2020). "Our results showed three additional genes, CAPN8, HDGF and RPS6KA1, may be involved in smoking-related mutational signature, mediated by gene expression altered by tobacco smoking in lung adenocarcinoma." (PMID 32928150, 2020). "Among them, the up-regulation of PRKCA and HDGF is considered to be a negative factor for the development of lung adenocarcinoma." (PMID 36339610, 2022). "In lung adenocarcinoma, our results showed that smoking increased the expression of three genes, AHRR, GPR15, and HDGF, and decreased the expression of two genes, CAPN8, and RPS6KA1, which were consequently associated with increased smoking-related mutational signature." (PMID 32928150, 2020).
nasopharyngeal carcinoma (3 papers, 2020 to 2021). A carcinoma arising from the nasopharyngeal epithelium. "A Chinese group identified that exosomal miR-9 derived from nasopharyngeal carcinoma cells inhibits angiogenesis by targeting Midkine (a heparin-binding growth factor) and regulating the PDK/AKT pathway in nasopharyngeal carcinoma." (PMID 32823989, 2020).